CSPG4 (chondroitin sulfate proteoglycan 4)
Diseases named in the same sentence as CSPG4 in open-access papers (continued):
Sharing a sentence is not in itself a finding about the gene and the disease.
melanoma (continued). "Live cell-imaging based scratch-wound assays of melanoma cells with stable knock-down of CD271 revealed a significantly reduced cell migration (3.9fold, p = 1.2E-04) and a reduced expression of FGF13, CSPG4, HMGA2 and AKT3 major candidate regulatory genes of melanoma cell migration." (PMID 28852061, 2017). "In addition to the observed effects on mRNA expression of CSPG4 and pro-MMP2, the expression of another gelatinase, MMP9, was also increased in the malignant melanoma cells and following silencing of ARSB." (PMID 27926479, 2017). "Since we observed co-expression of CSPG4 and CD271, a concerted action of both receptors may regulate melanoma cell properties." (PMID 28852061, 2017). "Although CSPG4 and CD271 are co-expressed in a subset of melanoma cells of MeWoPar (parental MeWo) and T20/02 (SI), their role in cell migration and metastasis might be different." (PMID 28852061, 2017). "Combined effects of increased C4S, CSPG4, and MMP2 increased the invasiveness of the melanoma cells, and therapy with recombinant ARSB may inhibit melanoma progression." (PMID 27926479, 2017). "In a study investigating a TRAIL-fused anti-CSPG4 scFv (based on the mAb 9.2.27), the novel therapeutic candidate showed potent in vitro activity against melanoma cell lines, but no off-target effects on normal melanocytes." (PMID 29375561, 2017). "In contrast, no anti-225D9+-TT Abs-induced shift in extracellular pH was observed in the CSPG4 negative M14 melanoma cell line." (PMID 25997619, 2015). "Although CSPG4 is over-expressed in over 80% of all melanomas, it is found at all disease stages and data so far have not yielded any correlations with disease progression." (PMID 25667918, 2014). "Both anti-CSPG4 IgE and IgG1 antibodies bound to CSPG4+ A375 human melanoma cells, but not to CSPG4− primary human melanocytes." (PMID 25073855, 2014). "Instead, full length CSPG4 and BRAF-V600E both appear to be required for sustained Erk 1,2 activation and a CSPG4-specific mAb enhanced and increased the duration of the effects of a BRAF inhibitor in melanoma cells." (PMID 24069584, 2013). "The fact that the majority of metastatic melanoma express these stem cell markers, and when present, neither MCAM or CSPG4 is expressed by a minor population of cells within the melanoma leads one to think about rare cancer stem cells in melanoma." (PMID 24069584, 2013). "Collectively, the data suggest that CSPG4 acts as a scaffold at the cell membrane to facilitate the formation of molecular complexes that stabilize integrins and receptor tyrosine kinases, and localize active MMP-2 to the melanoma cell surface." (PMID 24069584, 2013). "Notably, CAR-MαCSPG4 infiltrated the melanoma spheroid; whereas, CAR-MGFP localized primarily to the exterior of the melanoma spheroid, suggesting increased interactions between spheroids and CSPG4-targeting CAR-Ms versus control CAR-Ms." (PMID 40082557, 2025). "Thus, we selected CSPG4 as a target for proof-of-principle approaches to determine whether melanoma-targeting CAR-Ms will phagocytose melanoma cells and inhibit melanoma growth." (PMID 40082557, 2025). "Furthermore, combining CSPG4-targeting CAR-Ms with strategies inhibiting CD47/SIRPα “don’t eat me” signaling synergistically enhanced CAR-M-mediated phagocytosis and robustly inhibited melanoma spheroid growth in 3D." (PMID 40082557, 2025). "CSPG4, for instance, is only expressed in melanoma and not in healthy tissue." (PMID 39204391, 2024). "C57BL/6 mice were challenged subcutaneously with B16 melanoma cells that do not express CSPG4." (PMID 39409881, 2024). "A few other antigens, such as CSPG4 (glycoprotein and chondroitin sulfate proteoglycan), MC1R (melanocortin receptor group), DR5 (death receptor 5), and MSCP (glycoprotein and chondroitin sulfate proteoglycan) are currently being explored as targets for bispecific antibodies treating melanoma." (PMID 39204391, 2024).
melanoma (continued). "However, it is conceivable that based on the high expression and prevalence of CSPG4 in melanoma at all disease stages and its restricted distribution in normal tissues, future research will likely incorporate CSPG4 as a target for novel vaccine approaches." (PMID 39409881, 2024). "Immunohistochemistry (IHC) evaluations using a mouse anti-human CSPG4 antibody (detected by alkaline phosphatase (AP, pink)) in human melanomas (n = 428), and several normal tissues (n = 389) indicated detectable CSPG4 protein expression in 63% of malignant melanomas (n = 428)." (PMID 37185332, 2023). "In a posterior study, CSPG4, an epitope uniquely expressed on melanoma cells, was used to separate melanoma-derived exosomes from non-tumoral ones among serum exosomes (see the “Melanoma EV isolation” section)." (PMID 37022605, 2023). "The melanoma xenograft model with CD20+ Mel526 tumor cells clearly demonstrated that treatment with CSPG4-CAR T cells led to continuous tumor outgrowth, while robust tumor regression was only achieved upon treatment with dual-specific CSPG4-CAR_CD20-CCR T cells." (PMID 37901209, 2023). "Whilst cross-linking of NIP IgE (positive control) by its specific multimeric antigen (NIP-BSA) triggered significant degranulation, incubation with CSPG4 IgE with sera from healthy volunteers (n = 16) and patients with melanoma (n = 15) triggered no degranulation above background." (PMID 37185332, 2023). "In a recent preclinical study, the hypomethylating drug decitabine could be exploited to upregulate the well-established melanoma antigen chondroitin sulfate proteoglycan 4 (CSPG4) in originally CSPG4-negative ovarian cancer cells." (PMID 36768665, 2023). "In addition, expression of CSPG4 is not restricted to melanoma, but was also detected in various other cancer entities, and transfer of anti-CSPG4 CAR T cells controlled tumor growth in models of breast cancer, head and neck cancer, glioblastoma and sarcoma." (PMID 37849763, 2023). "Anti-CSPG4 DNA vaccination may emerge as a novel therapeutic approach in veterinary medicine to counteract OMM progression, with important implications for human melanoma patients." (PMID 35224082, 2022). "Native and glyco-engineered CSPG4-IgEs recognized Fc receptors on the surface of human FcεRI-expressing rat basophilic leukemia RBL-SX38 cells, and of CD23/FcεRII-expressing human RPMI-8866 B-lymphocytes and bound to CSPG4-expressing A2058 human melanoma cells, confirming Fab-mediated recognition." (PMID 36362241, 2022). "Proteomic profiling of melanoma-specific sEVs (CSPG4-captured) and non-malignant sEVs (non-captured) of 15 melanoma patients revealed 73 overexpressed proteins, of which 16 could discriminate melanoma-specific from non-malignant sEVs." (PMID 35804857, 2022). "In contrast, a control MOv18 IgE antibody, targeted toward a different antigen, folate receptor-alpha, which is not expressed by A375 melanoma cells, and used here as a nonspecific isotype control, showed much lower T/B and T/M ratios than those of the anti-CSPG4 antibodies at 24–120 h." (PMID 34513315, 2021). "Tumor cell viability was reduced in melanoma cell lines with high CSPG4 expression (A375, A2058) when treated with anti-CSPG4-(PDD), whereas a lower reduction in cell viability could be observed in the CSPG4-low WM-1361 cell line." (PMID 32331483, 2020). "Interestingly, CSPG4 has been shown to facilitate assembly of a ternary complex consisting of pro-MMP2, MMP-cleaving enzyme (MT3-MMP), and the proteoglycan itself at the cell surface of melanoma cells, leading to cleavage and thus activation of MMP2." (PMID 32984308, 2020). "Melanoma antigen-coated beads were recognized by an anti-CSPG4 antibody but not by MOv18 antibody specific for the antigen FRα not expressed by SK-MEL-28 cells, suggesting that antigen-reactive antibodies can specifically recognize antigen bound on these beads." (PMID 29628923, 2018).
melanoma (continued). "CSPG4 is not the only proteoglycan with C4S attachments, and other chondroitin sulfate proteoglycans, such as versican, may also be increased in the melanoma cells." (PMID 27926479, 2017). "Moreover, Chang and co-workers provided supporting evidence for non-immunological mechanisms by which anti-CSPG4 mAbs affect the biology of melanoma cells." (PMID 28657611, 2017). "Encouragingly, a phase I clinical trial investigating anti-CSPG4 radioimmunotherapy with a mAb (9.2.27) conjugated to an α-particle-emitting radioisotope which was administered systemically in patients with melanoma reported no adverse events while some clinical benefits were observed." (PMID 29375561, 2017). "However, CSPG4 expression in metastases was not significantly higher as compared to primary melanoma." (PMID 28852061, 2017). "A promising GBM associated antigen is the cell surface chondroitin sulfate proteoglycan NG2/CSPG4 that is also expressed on various cancer forms, including melanomas, leukemia, breast, and sarcomas, but not in normal differentiated cells in the corresponding tissues." (PMID 25972872, 2015). "CSPG4 IgE did not induce RBL-SX38 cell degranulation in the presence of patient sera and did not activate basophils in whole blood of patients with melanoma." (PMID 37185332, 2023). "No similar significant reduction in CSPG4 expression between early non-metastatic (Stage 0-II) and late metastatic (Stage III & IV) tumours was observed in melanoma." (PMID 36428658, 2022). "The CSPG4-specific CAR-T cells recognized the CSPG4-positive melanoma cell line A375M and responded with the production of IL-2, TNF, and IFNγ, while the CSPG4-negative target cell line 293T was not recognized." (PMID 31426437, 2019). "The CSPG4-specific scFv-Fc antibody reduced phosphorylation of both ERK1/2 and FAK by over 60% in CSPG4-positive cell lines, including melanoma, in the absence of immune effector cells, suggesting the suppression of melanoma growth through direct, Fab-mediated effects." (PMID 39409881, 2024). "We analyzed the relative expression of CSPG4 in human melanoma cell lines (A375, A2058, WM1366, WM115, WM1361, G361, and SKMEL28) in comparison to cells not known to express CSPG4 (IGROV1 ovarian and SKBR3 breast cancer cells, and primary non-malignant melanocytes)." (PMID 37185332, 2023). "Conspicuously, leukemia cells did not evoke IL-2 secretion from CSPG4-CAR T cells, whereas solid IL-2 secretion could be observed against melanoma cells." (PMID 31195686, 2019). "Since FGF13, CSPG4 and HMGA2 were not among the top up-regulated genes in the CD271high subset of brain metastases, these factors may not be involved in melanoma brain metastasis." (PMID 28852061, 2017).
breast carcinoma (57 papers, 2011 to 2026). "KM curves with Logrank test also identified high level of CSPG4 as a significant risk factor for overall survival in advanced breast cancers in TCGA-BRCA samples (P = 0.02)." (PMID 35280756, 2022). "We found that high level of CSPG4 was also a significant risk factor for OS in advanced breast cancers, suggesting a critical role for CSPG4 in determining the outcomes of advanced breast cancers." (PMID 35280756, 2022). "Among the PDL1high advanced breast cancers, CSPG4 high level was a significant risk factor for poor OS (P = 0.0493)." (PMID 35280756, 2022). "Among the PDL1low advanced breast cancers, CSPG4 high level was also a marginally significant risk factor for poor OS (P = 0.0730)." (PMID 35280756, 2022). "Another cancer type of epithelial origin, whose associations with CSPG4 have attracted a surge of interest, is breast cancer." (PMID 29375561, 2017). "However, the binding of VT68.2, but not 225.28, to cells was inhibited by N-glycosidase treatment, indicating that N-linked glycans contribute to VT68.2 reactivity with CSPG4 on MDA-MB-231 breast cancer cells." (PMID 36768830, 2023). "In addition, changes in CSPGs associated with breast cancer have been described, such as decorin or CSPG4." (PMID 23327652, 2013). "A known PG that carries CS-4 chains in breast cancer cells was cell surface associated CSPG4." (PMID 24205138, 2013). "The anti-CSPG4 monoclonal antibodies (mAbs) have shown anti-tumor activity and therapeutic potential for treating breast cancer." (PMID 36768830, 2023). "In this study, the reactivity of anti-CSPG4 mAbs was characterized with a peptide mimetic of carbohydrate antigens expressed in breast cancer." (PMID 36768830, 2023). "The effect of CSPG4 in conjugation with PDL1 overexpression on patient survival was further analyzed in advanced breast cancers by using the TCGA-BRCA database." (PMID 35280756, 2022). "Previous studies have shown that CSPG4 plays an important role in tumor cell proliferation and migration, as well as with poor prognosis and relapse in breast cancers." (PMID 34771455, 2021). "Mechanistically, interactions between chondroitin sulfate side chains of CSPG4 with P-selectin are thought to result in tumor cell activation and augment survival of circulating breast cancer cells." (PMID 33442419, 2021). "Increased expression of CSPG4 gene was correlated with disease reappearance in patients with breast cancer." (PMID 32315343, 2020). "With the central nervous system being a primary site of metastasis in breast cancer, CSPG4-CAR-T cells are expected to enter the brain, infiltrate metastatic lesions and mediate effector functions, such as cytokine secretion and target cell lysis." (PMID 31779130, 2019). "Mechanistically, interactions between chondroitin sulfate side chains of CSPG4 with P-selectin are thought to result in tumor cell activation and augmented survival of circulating breast cancer cells." (PMID 31779130, 2019). "The adhesion molecule P-Selectin evinces elevated expression on breast cancer cells and can be triggered by CSPG4 on the surface of cancer cells or by CSPG4-expressing stromal cells residing in the tumor microenvironment (TME)." (PMID 31779130, 2019). "Further experiments evaluating the effects of CSPG4 ablation on tumor growth in a murine breast cancer model revealed a reduced early progression phase." (PMID 31779130, 2019). "In this respect, it has been demonstrated that adipocyte-derived ColVI promotes early mammary tumor progression by binding the NG2/CSPG4 cell surface receptor and triggering the activation of the Wnt/β-catenin pathway." (PMID 31882701, 2019). "Further research is required to elucidate the CSPG4 pathological contributions to breast cancer formation and progression." (PMID 29375561, 2017). "Reportedly, CHST11 is overexpressed in aggressive breast cancers and facilitates the interaction between p-selectin and CSPG4." (PMID 29375561, 2017).
breast carcinoma (continued). "CSPG4 expression has previously been demonstrated on CSCs derived from squamous cell carcinoma of the head and neck and basal breast carcinomas." (PMID 25197555, 2014). "Analyses of gene expression profiles in breast cancer tissues suggest that CSPG4 expression is higher in Basal-type breast cancers, many of which are TN, than any other subtypes." (PMID 22984505, 2012). "Using the TCGA breast cancer gene expression data and the PAM50-based subtypes, we confirmed that the basal subtype breast cancers express significantly higher levels of CSPG4 transcripts compared to tumors of other subtypes." (PMID 22984505, 2012). "One-way between-subjects analysis of variance (ANOVA) was performed on the CSPG4 gene expression, as a function of breast cancer subtypes for basal, Her2-like, Luminal A, and Luminal B subtypes as determined by PAM50." (PMID 22984505, 2012). "CSPG4 is also expressed in various cancer cells including breast cancer cells and anti-CSPG4 antibody has been demonstrated to inhibit breast cancer growth and metastasis, suggesting a key role in promoting breast cancer progression and metastasis." (PMID 22984505, 2012). "We further showed that the expression of CHST11 and CSPG4 is elevated in tumor tissues from breast cancer patients." (PMID 21658254, 2011). "The carrier proteoglycan CSPG4 was highly expressed on the aggressive breast cancer cell lines and contributed to the P-selectin binding and CS-A expression." (PMID 21658254, 2011). "CSPG4 serves as a P-selectin ligand through its CS chain and participates in P-selectin binding to the highly metastatic breast cancer cells." (PMID 21658254, 2011). "Our data indicate that P-selectin binds to CSPG4 through CS-GAGs and that CSPG4 is involved in P-selectin binding to CSPG4-expressing breast cancer cells." (PMID 21658254, 2011). "Chondroitin sulfate proteoglycan 4 (CSPG4) is a cell surface proteoglycan that is expressed by various types of cancer cells and sarcomas, such as squamous cell carcinoma of the head and neck and breast cancer." (PMID 37872487, 2023). "Therapeutically, CSPG4 inhibition allows for efficient management of breast cancer." (PMID 35145999, 2022). "CSPG4 is a predictive marker for poor-onset tumors such as breast cancer and soft tissue sarcomas." (PMID 35128576, 2022). "Hence, CSPG4-CAR T-cells in TNBC can counteract this mechanism via down-regulating CSPG4 to impair metastasis and stunt breast cancer progression." (PMID 33442419, 2021). "Inhibition of CSPG4 is therapeutically effective for breast cancer therapy." (PMID 32245065, 2020). "Considering a wild-type situation, which can mimic the tumor microenvironment of human patients, several reports have shown a direct link between the expression of CHST11 (involved in decorating CSPG4 with chondroitin-4-sulfate) and the increased metastatic potential of breast cancer cells." (PMID 31949431, 2019). "Similarly, the anti-CSPG4 mAb 225.28 potently suppressed proliferation and metastasis in CSPG4+ breast cancer cells by inhibiting CSPG4-mediated survival-promoting signaling pathways." (PMID 28657611, 2017). "Together with chondroitin sulfate proteoglycan 4, selectin P can bind to highly metastatic breast cancer cells and removal of selectin P ligand could reduce metastatic lung colonization." (PMID 26975198, 2016). "It is well established that breast cancer cells do not synthesize significant amounts of matrix-secreted PGs, but mainly express cell-surface associated PGs, such as CSPG4, syndecans and glypicans, which promote tumor growth and spread." (PMID 24205138, 2013). "Thus, it is possible that CSPG4 expressed on breast cancer cells would transduce signals by forming a complex with NEDD9 for promoting migration, invasion, and growth in surrounding tissues." (PMID 22984505, 2012).